LINC01748 (long independently transcribed non-coding RNA 1748)
Gene: Long non-coding RNA gene on chromosome 1 (60,515,716 to 60,640,507, reverse strand). Ensembl gene ENSG00000226476.
Diseases named in the same sentence as LINC01748 in open-access papers:
LINC01748 is named in the same sentence as 5 diseases in open-access papers, as found by Europe PMC text mining. Sharing a sentence is not in itself a finding about the gene and the disease. The quoted sentences say what the papers report.
gastric cancer (1 paper, 2026). A primary or metastatic malignant neoplasm involving the stomach. "OBJECTIVE: The purpose of this study is to investigate the expression of linc01748 in gastric cancer (GC) tissues and cell lines, and to reveal the influence and potential mechanism of linc01748 on the biological behavior of GC cells." (PMID 41580854, 2026).
glioma (1 paper, 2025). A benign or malignant brain and spinal cord tumor that arises from glial cells (astrocytes, oligodendrocytes, ependymal cells). "Module 9 is highly specific in the undiffNPC cluster and includes several cancer-associated long non-coding (lnc) RNA genes (CASC15, NFIA-AS2, LINC01748, LINC00689, DNAJC27-AS1, and FEZF1-AS1) that are expressed in neuroblastoma, glioma, and other cancers." (PMID 40912258, 2025).
non-small cell lung carcinoma (1 paper, 2022). A group of at least three distinct histological types of lung cancer, including non-small cell squamous cell carcinoma, adenocarcinoma, and large cell carcinoma. "Moreover, LINC01748 regulates the miRNA-520a-5p/HMGA1 axis to exert carcinogenic effects in non-small cell lung cancer." (PMID 36212130, 2022).
cancer (2 papers, 2021 to 2025). A tumor composed of atypical neoplastic, often pleomorphic cells that invade other tissues. "Other cancer-related genes are ADAMTS17, LINC01748, LPAL2, SRP14-AS1 and WASH8P." (PMID 33672117, 2021).
LINC01748 also shares sentences with these, for which no sentence is quoted: neuroblastoma (1 paper).